IFNG (interferon gamma)
Diseases named in the same sentence as IFNG in open-access papers (continued):
Sharing a sentence is not in itself a finding about the gene and the disease.
infection (continued). "Infection of PCLS resulted in the robust secretion of IFNγ, followed by IFNL1, and IFNα2, while secreted IFNβ was unchanged (IFNγ>>IFNL1> IFNα2>> IFNβ)." (PMID 34899695, 2021). "In B6.Il10-/- mice, L. donovani infection induced a faster but transient activation of bone marrow monocytes, which correlated with the magnitude of CD4+ T cell production of IFNγ and resolution of the infection." (PMID 34557190, 2021). "GBP1 restricts infection in IFNγ-treated human mesenchymal stromal cells (MSCs) and lung epithelial cells (i.e., A549 cells) but not myeloid-derived cells (i.e., HAP1 cells)." (PMID 34871166, 2021). "(A) Representative histograms (top) and quantification (bottom) of CD69 MFI on NK cells and frequency of KLRG1+ and IFNγ+ NK cells at day 1.5 post-infection (pi) of 1αKO or FL control mice." (PMID 34396954, 2021). "To dissect the protective roles of TIPE proteins, we analyzed CD45+, CD4+, CD8+, IFNg- and TNFα-secreting cells in the lung at day 13 after infection." (PMID 34939151, 2021). "We show that IFNγ+ T-cell responses after infection are remarkably stable between three and twelve months post-infection." (PMID 34960185, 2021). "As expected, the pathways that interacted with TNF were the most, mainly cellular response to interferon-gamma-related anti-infection pathways." (PMID 34311758, 2021). "IFNγ activates macrophages to kill intracellular pathogens or phagocytosed bacteria and induces chemokines that attract immune cells to the site of infection." (PMID 34871329, 2021). "We also measured the levels of gene expression of the type II IFN (IFNγ) at days 3 and 6 post infection by RT-qPCR." (PMID 34925387, 2021). "Intracellular staining for IFNγ showed that most NK cells indeed produce this pro-inflammatory cytokine at 24 h post-infection, but its levels declined by 96 h, which suggests the time-regulated dual function of NK cells during Lm systemic infection." (PMID 35053151, 2021). "7-day-old neonatal mice have IFNγ producing CD8 T cells after infection with RSV, attenuated Vaccinia virus and attenuated Listeria." (PMID 33400715, 2021). "We described an enhanced compensatory CD4+ T cell effector function in TKO mice with increased IFNγ release during the course of infection." (PMID 33968021, 2021). "IFNγ treatment resulted in lower urea concentrations, nicely resembling the effects of cytokines and infection on Arg1 expression." (PMID 34359992, 2021). "A protective immune response to infection is of the Th1 type, activated by the S epitopes and characterized by the synthesis of IFNγ, IL-2, and TNF-α, while a predominantly Th2 response, with IL-4, -5, -13 synthesis can have detrimental effects." (PMID 34946179, 2021). "When comparison was made between different serotypes and primary/secondary infection, significant difference was observed in cytokines IL-1β, IL-2, IL-6, IL-8, IL-12, TNFα, IFNγ, GM-CSF, and IP-10." (PMID 34447698, 2021). "During STM infection we also observed an increased proportion of IFNγ/GM-CSF co-expressing lymph-migratory ILCs." (PMID 33414524, 2021). "In fact, N-specific IFNγ+CD107+ TRM were detected in five convalescent patients several months after infection." (PMID 34021148, 2021). "This would be in line with effects of iron restriction on IFNg formation and Th1 expression and improved immune control of infection." (PMID 34488018, 2021). "The attenuated infection arising from recently mosquito-transmitted parasites is characterised by an earlier and stronger myeloid- and IFNγ-related response." (PMID 34532703, 2021). "Here, we infected Hela cells with C. trachomatis and collected the inclusion body-containing host cells at 20 and 44 h post-infection (hpi), and also in the presence of interferon-gamma (IFN-γ) at 44 hpi." (PMID 33397284, 2021). "Culture supernatant was sampled 24 hours after infection and every 24 hours thereafter for five days and T-cell recognition quantified by measuring IFNγ in the supernatants by ELISA." (PMID 34882759, 2021).
infection (continued). "As such, we were curious to compare the roles of IFNγ and IFNβ on the replication of other macrophage-invading bacteria, such as Salmonella enterica serovar Typhimurium (STm) in our infection system." (PMID 33684179, 2021). "In many immune responses, mature IL-1β is an effective proinflammatory mediator, which can recruit innate immune cells to the infection site and regulate acquired immune cells, while mature IL-18 can promote expression of interferon gamma (IFN-γ)." (PMID 33860064, 2021). "Some of these changes, e.g. increases in mitochondrial mass were identified in NK cells from all vaccinated individuals, while others including mTORC1 activation, ATP5B expression and IFNγ production were largely dictated by prior infection with HCMV." (PMID 34584101, 2021). "This IFNγ signaling pathway inhibition was suggested to be the result of a decreased expression of IFN-gamma R-alpha protein after infection." (PMID 33898331, 2021). "Only infection with M. bovis 534 expressing ESAT-6 T63A (Mb534::ESAT6 T63A) increased the percentage of NKp46+IFNγ+ cells compared with the un-infected condition." (PMID 34335572, 2021). "IFNγ administration promptly after PR8 infection of mice increased lung NK cell numbers, cytotoxicity and improved resistance to infection, which was lost when NK cells were depleted." (PMID 34152253, 2021). "In case of DENV-1, significant downregulation in IFNγ (p<0.01) and upregulation in GM-CSF (p<0.01) were observed in primary compared to the secondary infection." (PMID 34447698, 2021). "When primary and secondary infection was compared within same serotypes, significant difference in expression was observed in IL-2, IL-8, IL-12, IFNγ, GM-CSF, and IP-10." (PMID 34447698, 2021). "Infection with S.tm induced Arg1 expression and IL-4 had an additive effect, whereas IFNγ reduced Arg1 mRNA expression." (PMID 34359992, 2021). "The antiviral effector function of NK cells was assessed by measuring IFNγ expression at 1.5 and 3.5 days post-infection." (PMID 34358016, 2021). "MAIT cells were found to be polarized to a Th1-like phenotype, with highest proportions, and numbers, of cells producing TNF, IFNγ, and GM-CSF, but few detectable IL-17-producing cells during the acute phase of infection (6 dpi)." (PMID 34272362, 2021). "LCMV-specific, IFNγ-producing CD8 T cells were found in the brain of neonates on day 9 post infection." (PMID 33400715, 2021). "On the protein level, infection with S.tm alone already caused induction of ARG1 protein, which was further increased in the presence of IL-4, but suppressed by IFNγ." (PMID 34359992, 2021). "Since both cognate Ag stimulation and IFNγ signaling are required for CD8+ TM cell–dependent protection of immunized hosts against challenge infection, we next assessed the relative contribution of both mechanisms." (PMID 34516896, 2021). "After 3 h and 6 h of infection, cells were processed for RT-qPCR to detect the mRNA levels of IFNα, IFNβ, IFNγ and NAA60." (PMID 35095845, 2021). "These combined results suggest the essential requirements for CD4+ T cells and IFNγ in protective immunity against challenge infection with B. microti." (PMID 34414129, 2021). "The use of knock-out strains for example, shed specific light on the role of various cytokines, particularly TNFα, IFNγ, and IL-10, in the control of parasitaemia and in the induction of pathological conditions during infection." (PMID 34114560, 2021). "IFNγ and IL-12 production is critical for protection against T. gondii, as IFNγ-/- mice or IL12p35-/- mice succumb to infection." (PMID 34938670, 2021). "A previous study showed mice infected with a genetically engineered C. neoformans strain expressing IFNγ can clear the infection." (PMID 35186781, 2021). "In adipose tissues, only IFNγ secretion increased after infection and this was blunted by CL316,243 treatment only in BAT." (PMID 34437647, 2021).
infection (continued). "Since IFNγ was previously shown to impair Mtb’s import of Bodipy-PA during macrophage infection, we tested if the cytokine also reduces Mtb’s uptake of other alkyne-FAs." (PMID 34951591, 2021). "EsxA and EsxB have been widely used in the specific diagnosis of infection with M. tuberculosis in interferon-gamma release assays." (PMID 33430286, 2021). "IFNγ-induced decrease in Fasn and Fads2 expression correlated with reduced Abca1 and Dhcr24 transcript levels after 6 hr of infection, suggesting that IFNγ prevents Mtb-induced stimulation of FA biosynthesis through downregulation of LXR and SREBP1 activity." (PMID 34951591, 2021). "Following infection with M. avium strain 25291 we found an increase in the percentage of LSK cells in the BM which is dependent on IFNγ." (PMID 34987496, 2021). "Our results showed in the cerebellum a significant increase in the expression of TNFα and IFNγ from day 1 and for IL-12 from day 14 post-infection." (PMID 33322180, 2020). "Non-typeable H. influenzae (NTHi) induces a potent inflammatory response upon infection, including IL-8, TNFα, and IFNγ." (PMID 33101299, 2020). "During the first week of infection, several proinflammatory cytokines are produced, preferentially IFNγ by the host natural killer cells." (PMID 33376582, 2020). "To extend these findings to the in vivo situation, we determined serum concentration of IFNγ as well as cytokines and chemokines five weeks after infection." (PMID 32408806, 2020). "We infected mice with LCMV Armstrong and checked T-cell phenotype and IFNγ expression at different time points (3, 5, 8, 12, and 24 days after infection)." (PMID 33488602, 2020). "Hierarchical clustering revealed groups of differentially regulated proteins either positively or negatively correlating with the cell death gradient as well as clusters of proteins regulated by IFNγ-priming in an infection-independent manner." (PMID 33378358, 2020). "When we measured IFNγ-responses in PBMCs by ELISpot prior to H2N2 infection, we observed not only responses to H1N1, but also against H2N2 in primed animals." (PMID 33037319, 2020). "RAR signaling-dependent IL-18 promotes epithelial cell shedding as well as mucosal IFNγ production to orchestrate resistance to infection." (PMID 32330185, 2020). "Animal studies have also shown increased levels of tumor necrosis factor-alpha (TNFα) and interferon-gamma (IFNγ) during infection." (PMID 33224678, 2020). "The amount of IFNγ producers also decreases, but they are still detectable even 24 days after infection (1.43% of Ly49+CD8 T-cells produce IFNγ in response to gp33 comparing to 3.6% of conventional memory CD8 T-cells)." (PMID 33488602, 2020). "Infection of early and term placental cultures resulted in suppression of IFNγ-induced IDO expression." (PMID 33374185, 2020). "Most notably, MTBVAC-HK boosting significantly suppressed the PPD-specific IFNg response up until 6 weeks after infection." (PMID 32625195, 2020). "Even though we did not observe significant changes in platelets in hyperacute HIV infection, there was a positive correlation between post-infection platelet counts and interferon gamma during the hyperacute phase (rho = 0.62, P = 0.024)." (PMID 32209092, 2020). "As expected, the naturally derived population of RSV-specific IFNγ-producing CD8+ T cells in peripheral circulation in response to the infection declines with age." (PMID 33317695, 2020). "All knockouts had reduced growth compared to wild-type parasites in IFNγ-activated BMDMs as determined by luciferase assays at 24 h post-infection (p.i.)." (PMID 33067458, 2020). "To investigate a potential role for Syk in the response of BMMs to IFNγ stimulation and F. tularensis LVS infection, we evaluated the effects of Syk inhibition in regulating the production of IFNγ‐induced NO." (PMID 32841534, 2020). "We observed that infection led to increased expression, particularly of IFNα, IFNγ, IL1β, and IL6 on day 1 post‐challenge." (PMID 32319216, 2020).
infection (continued). "The majority of naïve subjects respond to blood-stage infection with the secretion of IFNγ by γδ T cells and NK cells, as well as αβ T cells and levels of IFNγ continue to increase for a week after treatment." (PMID 31900030, 2020). "Interferon gamma release assays (IGRA) use T cell-based Interferon-gamma (IFN-γ) to identify infection with M. tuberculosis (MTB) but cannot discriminate between active and LTBI." (PMID 32099659, 2020). "IFNγ was neutralised at day −1 and 1 of infection in Il17a-KO and WT mice, and responses examined at d8pi, a time point when the type-2 response should be fully developed." (PMID 32636457, 2020). "At early stages of acute infection, and as a result of IL-12 signaling, NK cells produce IFNγ, which helps to control the parasite prior to T cell activation." (PMID 33120910, 2020). "For example, when exogenous IFNγ is added to an infection culture, Sts−/− cells are able to clear intracellular CFUs more effectively than wild type cells." (PMID 32841534, 2020). "Seven days after infection, splenocytes were collected and stimulated with each HLA A2-restricted peptide in an IFNγ-ELISpot assay." (PMID 33101303, 2020). "Mice were infected as above and starting at week 5 post infection we assessed NK cell (CD3–CD49b+ NKp46+) function (IFNγ × CD107a) by flow cytometry." (PMID 32733814, 2020). "Comparison of the ability of IFNα and IFNγ to block infection demonstrated that IFNγ has more pronounced effects on VZV replication in human embryonic lung fibroblasts." (PMID 32038653, 2020). "In case of infection and inflammation, IFNγ acts as a pro-osteoclastogenic agent leading to an increased bone resorption." (PMID 33182721, 2020). "Control of infection and the resistance to subsequent infections was shown to be both IFNγ and T-cell-dependent, again mirroring what is seen in human cryptosporidiosis." (PMID 32167464, 2020). "This CD4 T cell response is mainly mediated by Tbet-expressing, IFNγ-secreting Th1 cells, and it is necessary for resistance to the infection and final clearance of the bacteria in the tissues." (PMID 33042146, 2020). "Similar to infection with N. brasiliensis, we also observed an upregulation of IFNγ in the lung during T. muris infection in Il17a-KO mice." (PMID 32636457, 2020). "One study found that IFNγ knockout mice had higher survival rates and lower bacterial burdens during intravenous infection compared to wild type controls." (PMID 33291260, 2020). "They secrete pro-inflammatory cytokines such as interferon gamma (IFNγ) to promote bacterial clearance and halt systemic spread of the infection." (PMID 32330185, 2020). "Within 7–8 days after infection infectious virus is cleared from neurons through the antiviral effects of antibody and interferon-gamma (IFNγ), but RNA persists." (PMID 32210257, 2020). "Carcass inspection has shown to be insufficient to detect infection in swine; thus, the assessment of intradermal tuberculin test and interferon-gamma release assay (IGRA) in this species is mandatory." (PMID 33392284, 2020). "T cells and natural killer (NK) cells produce high levels of interferon-gamma (IFNγ) at sites of infection, which dissipates upon resolution of infection (Thäle and Kiderlen, 2005)." (PMID 32610126, 2020). "In the current study, we identify IFNγ as a critical cytokine that promotes the enhanced microbicidal activity of Sts−/− BMMs in the context of the ex vivo infection assay." (PMID 32841534, 2020). "The frequencies and numbers of IFNγ‐positive NK cells were increased in the spleens and livers of Trail−/− versus WT mice, most prominently 24 h after infection." (PMID 31742873, 2020). "Although activated T-cells and natural killer cells are regarded as the major source of IFNγ during early infection, macrophages are also capable of secreting this cytokine in the presence of IL-12 and IL-18." (PMID 33352656, 2020).
infection (continued). "Ab4-wt infection blocks IFNγ release from PBMC and deleting ORF1 gene resulted in release of more cytokines/chemokines which shows the immune-modulating potential of ORF1 in Ab4 strain." (PMID 32911663, 2020). "Infections of IFNγ-primed SNU-C5 and HT-29 with EPEC-1 resulted in higher cell death compared with those with EPEC-0." (PMID 33378358, 2020). "In contrast, IFNγ priming increased PI uptake to 27% and 51% following infection with EPEC-WT and EPEC-1, respectively." (PMID 33378358, 2020). "At different time points of infection, single lung cell suspensions were prepared, and intracellular staining of IFNγ in CD4+ T cells was performed after 4 hrs of incubation in medium or after restimulation with anti-CD3/CD28." (PMID 33375150, 2020). "IFNG is an important cytokine in the host defense against infection by viral and microbial pathogens." (PMID 32342250, 2020). "In contrast to the Type 2 immune response present at later stages of infection, a robust Type 1 immune signature including IFNg production was dominant at the time of parasite invasion and granuloma formation." (PMID 31776431, 2020). "Upon the infection of IFNγ-activated HBDM with the M. avium strains, the lysX mutant induced a higher rate of macrophage fusion than the wild type and the complemented strain." (PMID 31996090, 2020). "In TB, IL-17A contributes indirectly to granuloma formation and the recruitment of IFNγ/TNF/IL-2-producing multifunctional T cells to the site of infection by the induction of various chemokines." (PMID 33334075, 2020). "Treatment with celecoxib reduced Mtb CFU in a dose-dependent manner across the conditions including infection alone or when treated with IFNγ, TNFα, or MK571." (PMID 32546788, 2020). "In contrast to BHK cells, dAP7 cells treated 2 h after infection with anti-E2 antibody or IFNγ alone or in combination decreased intracellular viral RNA by 24 h and most cells cleared viral RNA by 72 h." (PMID 32210257, 2020). "That implies that secretion of IFNγ alone or in combination with perforin are required for CD8 T cells to control the infection." (PMID 32973802, 2020). "IFNγ, a key pro-inflammatory cytokine, is highly expressed during C. parvum infection, and is critical to the resolution of infection." (PMID 33113928, 2020). "In murine models of Rickettsia infection, it was also suggested that the infection seems to be controlled initially by NK cells through IFNγ secretion, prior to the late response of CD8+ T cells." (PMID 33120910, 2020). "At 14 days post infection (directly after treatment) very high concentrations of IL-2, IL-13, IL-10, IFNγ, IL-6, and TNFα were observed." (PMID 32226027, 2020). "Accordingly, measurement of IFNγ produced by T cells is the most widely used method for detecting immune responses following infection or vaccination with BCG." (PMID 32218774, 2020). "Analysis of the cytokine subsets in the uGT showed that the Th1 effector cytokine subsets expressing TNFα/IFNγ and TNFα/IFNγ/IL-2 were present at day 14 and day 21 post infection." (PMID 31993218, 2020). "A similar result was obtained when cells were primed with IFNγ for 2 hours before a 4 hour infection with LVS." (PMID 32841534, 2020). "Diminished production of inflammatory cytokines and increased IFNγ were detected in the blood of immunized cows, where a T lymphocyte activation profile was evidenced at 12-h post infection." (PMID 33298970, 2020). "The highest IFNγ responses were seen in those with mild infection, which were higher than those who had mild illness, but prolonged shedding." (PMID 33199778, 2020). "High levels of interferon-gamma are indicative of ongoing infection, and in its absence, activated macrophages appear to engage a “default” Spic-dependent anti-inflammatory pathway." (PMID 32610126, 2020).